TRAPPC2 (trafficking protein particle complex subunit 2)
Description:
Prevents transcriptional repression and induction of cell death by ENO1 (By similarity). May play a role in vesicular transport from endoplasmic reticulum to Golgi.
Synonyms: SEDL; TRS20; SEDT; MIP-2A; ZNF547L; hYP38334; MIP2A; TRAPPC2P1
Tractability: PROTAC: ubiquitination databases record sites on it.
Gene: Protein-coding gene on chromosome X (13,712,244 to 13,734,635, reverse strand). Ensembl gene ENSG00000196459.
Subcellular location: Cytoplasm, perinuclear region; Endoplasmic reticulum-Golgi intermediate compartment; Nucleus; Cytoplasm
Subcellular location (Human Protein Atlas): Endoplasmic reticulum; Vesicles; Nucleoplasm
Pathways (Reactome):
Vesicle-mediated transport: COPII-mediated vesicle transport; RAB GEFs exchange GTP for GDP on RABs
Gene Ontology:
Molecular function: protein binding; transmembrane transporter binding
Biological process: skeletal system development; COPII vesicle coating; endoplasmic reticulum to Golgi vesicle-mediated transport; vesicle coating
Cellular component: cytoplasm; endoplasmic reticulum; endoplasmic reticulum-Golgi intermediate compartment; nucleus; perinuclear region of cytoplasm; TRAPP complex; cytosol; TRAPPII protein complex; TRAPPIII protein complex
Homologues: Orthologues: chimpanzee TRAPPC2B (100% identical), macaque TRAPPC2 (100% identical), guinea pig Trappc2 (99% identical), mouse Trappc2 (98% identical), tropical clawed frog trappc2 (86% identical), dog TRAPPC2 (82% identical), rabbit TRAPPC2 (63% identical). Paralogues in human: TRAPPC2B (100% identical), TRAPPC2L (26% identical).
Diseases named in the same sentence as TRAPPC2 in open-access papers:
TRAPPC2 is named in the same sentence as 17 diseases in open-access papers, as found by Europe PMC text mining. Sharing a sentence is not in itself a finding about the gene and the disease. The quoted sentences say what the papers report.
X-linked spondyloepiphyseal dysplasia tarda (7 papers, 2011 to 2026). "X-linked spondyloepiphyseal dysplasia tarda (X-linked SEDT) is a rare hereditary cause in childhood short stature due to mutations in trafficking protein particle complex subunit 2 (TRAPPC2) gene located on chromosome Xp22." (PMID 33726005, 2021). "For example, TRAPPC2 is implicated in X-linked spondyloepiphyseal dysplasia tarda (SEDT), associated with skeletal abnormalities and short stature." (PMID 29391579, 2018). "Mutations in TRAPP subunits TRAPPC9 and TRAPPC2 have been identified in patients with mental retardation and X-linked spondyloepiphyseal dysplasia tarda (SEDT), respectively." (PMID 21858081, 2011). "Mutations in the TRAPP complex subunit 2 (TRAPPC2) cause X-linked spondyloepiphyseal dysplasia tarda, while mutations in the TRAPP complex subunit 9 (TRAPPC9) cause postnatal mental retardation with microcephaly." (PMID 21858081, 2011). "Similarly, the ER export of procollagen is also controlled in part by the ubiquitously expressed Sedlin (TrappC2), and antimorphic or loss of function mutations in TRAPPC2 cause X-linked spondyloepiphyseal dysplasia Tarda (SEDT)." (PMID 26635999, 2015). "Mutations affecting trafficking protein particle complex 2 (TRAPPC2 or Sedlin) and dymeclin, thought to have roles in protein transport between ER and Golgi, also cause nonlethal skeletal dysplasias, X-linked spondyloepiphyseal dysplasia tarda and Dyggve-Melchior-Clausen syndrome, respectively." (PMID 30439444, 2019).
spondyloepiphyseal dysplasia tarda (6 papers, 2011 to 2023). Spondyloepiphyseal dysplasia tarda (SEDT) is characterized by disproportionate short stature in adolescence or adulthood, associated with a short trunk and arms and barrel-shaped chest. "Spondyloepiphyseal dysplasia tarda (SEDT) is a rare X-linked recessive inherited osteochondrodysplasia caused by mutations in the TRAPPC2 gene." (PMID 32471379, 2020). "Mutations in TRAPPC1 (MUM-2) were reported to result in expression of antigenic peptides in melanoma, and mutations in TRAPPC2 (sedlin) have been linked to Spondyloepiphyseal dysplasia tarda (SEDT)." (PMID 21826244, 2011). "Spondyloepiphyseal dysplasia tarda (SEDT) is a condition involving late-onset, X-linked recessive skeletal dysplasia caused by mutations in the TRAPPC2 gene." (PMID 37693308, 2023).
Intellectual disability (2 papers, 2011 to 2018). "Mutations have previously been reported in several members of the TRAPP complex of proteins, including TRAPPC2, TRAPPC9 and TRAPPC11, resulting in disorders involving skeletal abnormalities, intellectual disability, speech impairment and developmental delay." (PMID 29391579, 2018). "In a similar experiment, we have further identified that the carboxyl terminus of TRAPPC9 is required for its interaction with TRAPPC2 and TRAPPC10, as deletional mutants of this domain found in some patients with intellectual disability failed to interact with TRAPPC2 or TRAPPC10." (PMID 21858081, 2011).
osteoarthritis (2 papers, 2020 to 2021). A noninflammatory degenerative joint disease occurring chiefly in older persons, characterized by degeneration of the articular cartilage, hypertrophy of bone at the margins and changes in the synovial membrane. "These intrafamilial phenotypic differences could have possibly resulted from the penetrance of TRAPPC2 mutations and the course of progressive osteoarthritis." (PMID 32471379, 2020).
Allergy (1 paper, 2024). An allergy is an immune response or reaction to substances that are usually not harmful. "The specific SNPs of allergy and non-allergic groups were mainly in trafficking protein particle complex subunit 2 (TRAPPC2), Pirin (PIR), complement factor properdin (CFP), and sosondowah ankyrin repeat domain family member D (SOWAHD), however only TRAPPC2 and PIR were non-synonymous mutations." (PMID 39881721, 2024).
chondrosarcoma (1 paper, 2023). A malignant cartilaginous matrix-producing mesenchymal neoplasm arising from the bone and soft tissue. "Here, siRNAs were used to knock down TRAPPC2 expression in the chondrosarcoma cell line SW1353 and primary chondrocytes." (PMID 37693308, 2023).
limb-girdle muscular dystrophy (1 paper, 2024). Limb-girdle muscular dystrophy (LGMD) is a heterogeneous group of muscular dystrophies characterized by proximal weakness affecting the pelvic and shoulder girdles. "For example, the TRAPPC2 subunit is the only subunit where pathogenic variants lead to a skeletal disorder, whilst TRAPPC11 has a unique limb girdle muscular dystrophy phenotype in humans." (PMID 39769094, 2024).
Miscarriage (1 paper, 2015). A pregnancy that ends at a stage in which the fetus is incapable of surviving on its own, defined as the spontaneous loss of a fetus before the 22th week of pregnancy. "TRAPPC2 and OFD1 had increased RNA and protein expression in miscarriage 9-3B with a gain of Xp22.2." (PMID 25674159, 2015). "Three genes, OFD1, TRAPPC2 and TIMP2 out of 14 selected for expression analysis had altered mRNA and protein expression in cultured miscarriage chorionic villi cells." (PMID 25674159, 2015).
Obesity (1 paper, 2024). Accumulation of substantial excess body fat. "However, patients bearing mutations of Trappc2, Trappc2l, Trappc4, Trappc6A/B, or Trappc10 do not develop obesity as patients with Trappc9 mutations do." (PMID 38889014, 2024).
osteochondrodysplasia (1 paper, 2020). A term referring to disorders characterized by abnormalities in the development of bones and cartilage. "All of them deprive the cells of TRAPPC2 function, leading to osteochondrodysplasia." (PMID 32471379, 2020).
cancer (1 paper, 2021). A tumor composed of atypical neoplastic, often pleomorphic cells that invade other tissues. "Many of the genes in this category are known oncogenes or tumor suppressors (e.g., DDX3X, TRAPPC2, and TCEANC), they play crucial roles in women’s cancer." (PMID 34725332, 2021).
neurodevelopmental disorder (1 paper, 2018). A behavioral and cognitive disorder with onset during the developmental period that involves impaired or aberrant development of intellectual, motor, or social functions. "In summary, TRAPPC6A potentially adds to a growing list of TRAPP complex proteins (TRAPPC2, TRAPPC9, TRAPPC11), including the closely related TRAPPC6B, involved in neurodevelopmental disorders." (PMID 29391579, 2018).
TRAPPC2 also shares sentences with these, for which no sentence is quoted: skeletal dysplasia (3 papers); spondyloepiphyseal dysplasia (2); developmental delay (1); melanoma (1); microcephaly (1).